SIRT1 (sirtuin 1)
Diseases named in the same sentence as SIRT1 in open-access papers (continued):
Sharing a sentence is not in itself a finding about the gene and the disease.
breast cancer (continued). "This is the first report showing that SIRT-1 induction is essentially required for lipid metabolic remodeling of lipids and suppression of breast cancer growth by adiponectin." (PMID 34986886, 2022). "Another study found that miR-590-3p expression is downregulated in MCF-7 and MDA-MB-231 breast cancer cells, and miR-590-3p exerts its antitumor effects (induction of apoptosis and reduction of cell survival) by targeting SIRT1 in breast cancer cells." (PMID 36291902, 2022). "For instance, the transcription of CYP19A1 (a gene encoding the aromatase enzyme) was downregulated in MDA-MB-231 breast cancer cells expressing aromatase following the inhibition of SIRT1 by treatment with both cambinol and inhibitor VII." (PMID 36291902, 2022). "Conversely, a previous study reported that SIRT1 represses estrogen receptor activation by deactivating Akt activity to suppress the growth of MCF-7 breast cancer cells." (PMID 36291902, 2022). "As recent studies reported, a downregulation of SIRT1 has already been described in gastric cancer and breast cancer." (PMID 35250881, 2022). "The authors further demonstrated that miR-22 negatively regulates the expression of SIRT1, and SIRT1 ectopic expression reversed the inductive effect of miR-22 on apoptosis and the radiosensitivity of breast cancer cells." (PMID 36291902, 2022). "Surprisingly, while the evidence clearly indicates a context-dependent role of SIRT-1 in breast cancer, little is known about the involvement of cellular metabolic modulation by SIRT-1 in its pro-oncogenic and anti-oncogenic actions." (PMID 34986886, 2022). "Given the limited information in the literature to date, we discuss the current information on the mechanistic role of miRNA-mediated regulation of SIRT1 and 7 in breast cancer and SIRT1 in prostate cancer and elucidate a common mechanism for this regulation." (PMID 36291902, 2022). "Of note, SIRT1 has been highlighted for regulating radiosensitivity of hepatoma cells and breast cancer cells." (PMID 35183223, 2022). "Several miRNAs have been found to regulate SIRT1 expression in breast cancer, serving as either tumor suppressors or tumor promoters through an indirect mechanism, depending on their effect on SIRT1 expression." (PMID 36291902, 2022). "In summary, our works demonstrate that 4 autophagy-related mRNA (APOL1, HSPA8, SIRT1, and TP73) are significantly associated with the early relapse of breast cancer during the postoperative follow-up." (PMID 35250881, 2022). "It has been shown that downregulation of miR-22 is accompanied by overexpression of SIRT1 in breast cancer tissues." (PMID 35087589, 2022). "The authors suggested the crosstalk between the mitochondrial and nuclear sirtuins following SIRT1 downregulation by SIRT4 expression culminated in the suppression of breast cancer." (PMID 36291902, 2022). "As a mechanism, the authors suggested that the SIRT1-mediated inhibition of the proliferation of the breast cancer cells was due to the downregulation of c-Myc, which resulted in the downregulation of MTDH." (PMID 36291902, 2022). "There are numerous studies reporting high expression levels of SIRT1 in cancers, such as breast cancer, colorectal adenocarcinoma, hepatocellular carcinoma, soft tissue sarcomas, prostate cancer, ovarian and cervical cancers, lymphoma, and GC." (PMID 36499440, 2022). "It is the first polyphenol reagent recognized as an activator of SIRT-1/3/7, whose cytotoxic effects on breast cancer cells depend on SIRT-1." (PMID 35906622, 2022). "The protein expression of PRRX1, a transcription factor that induces epithelial-to-mesenchymal transition (EMT) and inhibits cancer stemness, was shown to be downregulated by SIRT1 gene silencing in mouse 4T1 breast cancer cells." (PMID 36291902, 2022).
breast cancer (continued). "It is also notable that blockage of SIRT-1 prevented lipid depletion, lipid raft disruption, and lipophagy activation by gAcrp, further confirming that SIRT-1 drives lipid metabolic reprogramming in adiponectin-stimulated breast cancer cells." (PMID 34986886, 2022). "miR-4766-5p impeded the developing process of tumors by regulating different targets, including SIRT1 in breast cancer and NKAP in GC." (PMID 34616917, 2021). "TFEB, SIRT1, and Beclin-1 seem to have a potential prognostic significance in patients with chemo-treated breast cancer, likely because of their role in the regulation of autophagy." (PMID 34663249, 2021). "Our preliminary data demonstrate a potential prognostic value of TFEB, SIRT1, and Beclin-1, likely for their role within autophagy regulation in patients affected by breast cancer and treated with anti-blastic therapy." (PMID 34663249, 2021). "In MCF7 breast cancer cells, overexpression of SIRT1 increased the proliferation, migration, and motility by increasing the POLD1 expression." (PMID 34650436, 2021). "In models of breast cancer metastases and kidney fibrosis, SIRT1 suppressed EMT by deacetylating Smad4 and thus, repressing TGFβ-induced MMP7." (PMID 33946753, 2021). "Regarding SIRT1, there are reports which describe a correlation between its increased expression and a poor prognosis in breast cancer." (PMID 34663249, 2021). "Cambinol markedly decreases aromatase levels in human breast cancer cells by inhibiting SIRT1-mediated deacetylation and transcription activity of estrogen-related receptor α." (PMID 33435263, 2021). "In breast cancer cells, SIRT1 was found to deacetylase mitogen-activated protein kinase 1 (MAP2K1), leading to inactivation of the MEK/ERK cell signaling pathway and reduction in FOXM1 protein." (PMID 34680943, 2021). "For instance, miR-4766-5p impeded the development of breast cancer by downregulating the expression of SIRT1." (PMID 34616917, 2021). "c-Myc and SIRT1 are commonly found in aggressive breast cancer tissues, making them potential therapeutic targets." (PMID 34959644, 2021). "Notch1 signaling has been reported as a downstream effector pathway of SIRT1 to affect disorder progression, such as liver fibrosis, breast cancer, and lung cancer." (PMID 34961513, 2021). "• TFEB, SIRT1, and Beclin-1 seem to have a potential prognostic significance in patients with chemo-treated breast cancer." (PMID 34663249, 2021). "An investigation of fatty acid oxidation (FAO) in breast cancer reported that PML enhances FAO through PPAR signaling by inducing the deacetylation of PPAR-γ coactivator 1α (PGC1α) by Sirtuin 1 (SIRT1)." (PMID 34830976, 2021). "In the present study, we tried to explore the potential role of radioactivity by evaluating expression protein levels of SIRT1 and 2 in breast cancer patients." (PMID 33705642, 2021). "Zhang and collaborators reported that Sirt1 is a direct target of miR-22, and their expression is antagonistic, so miR-22 improves radiosensitivity to breast cancer cells by targeting Sirt1." (PMID 34804940, 2021). "Isoalantolactone, a derivative of AL, induces apoptosis of human breast cancer cells through ROS-mediated mitochondrial pathway and down-regulation of SIRT1 expression." (PMID 33927214, 2021). "SIRT1 is known to be a significant prognostic factor in many cancers, and a high SIRT1 expression is known to be an unfavorable prognostic factor in breast cancer." (PMID 34663249, 2021). "Recent studies demonstrate that SIRT1 is upregulated in breast cancer cells and tissues, facilitates cell proliferation, colony formation and cell migration in vitro and promotes tumorigenesis in vivo." (PMID 34413268, 2021). "The level of SIRT1 is also markedly elevated in cancer cells such as acute and chronic leukemic cells, prostate and breast carcinoma." (PMID 34837933, 2021). "Supportively, previous studies confirmed the targeting relationship between SIRT1 and miR‐200a in breast cancer." (PMID 32324317, 2020).
breast cancer (continued). "The T-box protein Brachyury, a transcription factor, promotes the resistance of breast cancer cells to tamoxifen by inhibiting SIRT1." (PMID 33362547, 2020). "In conclusion, we found that SIRT4 regulation of BITCs negatively modulated mammary tumorigenesis through suppression of SIRT1 via glutamine metabolism and that SIRT4 deficiency decreased H4K16ac and BRCA1 expression in breast cancer." (PMID 32863939, 2020). "SIRT1 plays a tumor-suppressor role in various human cancers, including breast cancer, bladder cancer, and glioblastoma." (PMID 32158696, 2020). "SIRT1 expression is highly elevated by stimulated 17-β-estradiol (E2) levels in most ERα-positive breast cancer samples while SIRT1 inhibition leads to ER signaling inhibition implying SIRT1 role as ERα co-activator." (PMID 33330467, 2020). "SIRT1 expression is upregulated in some cancers, such as prostate and colon cancer, and downregulated in others, such as breast cancer and hepatic cell carcinoma, suggesting that SIRT1 has different roles depending on cellular context." (PMID 32151067, 2020). "Meanwhile, SIRT1 activation in BRCA1 overexpressed breast cancer cells inhibited AR expression and AR-stimulated cancer cell proliferation." (PMID 33330467, 2020). "In breast cancer tissue elevated Sirt1 expression correlates with tumor size, high histological grades and lymph node metastasis." (PMID 32426286, 2020). "The implications of SIRT1 in breast cancer occurrence and progression have been investigated over recent years." (PMID 32863939, 2020). "Here, we show that SIRT4 possesses its tumor-suppressive effect on breast cancer by inhibiting glutamine metabolism and thereby affecting the protein levels of SIRT1, which modulates the acetylation patterns of histones H4 and regulates stemness via BRCA1." (PMID 32863939, 2020). "This study further indicated that SIRT1 reduced the tumorigenesis of breast cancer by altering the lysosomal activity." (PMID 33344455, 2020). "Upregulation of Sirt1 expression in many cancer types such as breast cancers, leukemia, prostate, and colon cancers also support the tumor promoter role of Sirt1." (PMID 32698385, 2020). "NAM-induced SIRT1 or PARP1 suppression also enhances sensitivity to chemotherapy in breast cancer cell lines." (PMID 32245130, 2020). "Taken together, these results indicate that PARP-1, H1, and SIRT-1 directly interact in an aromatase promoter I.3/II-region crucial for the induction in BAFs in the vicinity of breast cancer cells in vivo." (PMID 32059481, 2020). "Among them, downregulation of miR-590-3p is common especially in breast cancer, which is negatively correlated with SIRT1 expression and coinhibits cell survival and induces cancer cell apoptosis." (PMID 32565880, 2020). "Similar to other HDACs, aberrant SIRT1 expression is reported in multiple human malignancies, namely, gastric, colon, prostate, and ovarian cancers, as well as breast cancer 5-11." (PMID 32863939, 2020). "Previous study indicated that the expression of the SIRT1 level was markedly lower in the tumor tissues of breast cancer, prostate cancer, bladder cancer, ovarian cancer, and glioblastoma as compared to normal tissues 39,40." (PMID 32398958, 2020). "To prove the involvement of SIRT1 in SIRT4-deficiency-induced malignancy, we established stable breast cancer cell lines (MDA-MB-468 and MCF-7) expressing two independent shRNAs that target SIRT1 and SIRT4." (PMID 32863939, 2020).
breast cancer (continued). "Sirtuins can promote or suppress breast cancer metastasis, and several sirtuin modulators (including selisistat, a SIRT1 inhibitor) have been investigated in clinical trials." (PMID 33613454, 2020). "On the other hand, SIRT1 down regulation has also been observed in other neoplasms, such as breast cancer and hepatic cell carcinomas." (PMID 31261609, 2019). "It has been determined that levels of SIRT1 increased significantly in hepatocellular carcinoma, breast cancer, glioblastoma, lymphoma, and other types of cancer development and invasion." (PMID 31747893, 2019). "Studies showed that silencing SIRT1 inhibited cell proliferation and tumor formation in some human cancer cell lines such as non‐small‐cell lung cancer and breast cancer." (PMID 30918653, 2019). "A key regulator of H3K9 acetylation is the NAD-dependent histone deacetylase SIRT1 that is overexpressed in many types of cancer including breast cancer." (PMID 31816600, 2019). "SIRT1 overexpression in breast cancer cells reduces EMT in nude mice, while SIRT1 repression increases EMT." (PMID 30761005, 2019). "SIRT1 is involved in the initiation, promotion, and progression of several malignant tumors including prostate cancer, breast cancer, lung cancer, leukemia, colon cancer, melanoma, and ovarian and gastric cancer." (PMID 30761005, 2019). "A decrease in SIRT1 in breast cancer is correlated with BRCA1 mutations, which indicates the role of SIRT1 as a tumor suppressor." (PMID 31817470, 2019). "After treatments with NSAIDs and exisulind, the basal acetylation remained unchanged firmly demonstrating the direct role of SIRT1 in mediating the K382 acetylation induced by these compounds in breast cancer cells." (PMID 30739913, 2019). "Upregulation of SIRT1 has been reported in breast cancer, prostate cancer, acute myeloid leukemia, and primary colon cancer." (PMID 31781300, 2019). "Contrary to SIRT1 and SIRT2, SIRT3 is reported to have an opposing effect on angiogenesis, as loss of SIRT3 in human breast cancers, resulted in the upregulation of HIF-1α target genes like VEGF and genes involved in glycolysis." (PMID 32010617, 2019). "In this study, we aim to determine the anti-cancer effects of ISO against breast cancer cell survival and proliferation, possibly through regulating SPHKs, tubulin destabilization and Sirt1 activation." (PMID 31817453, 2019). "In MCF7 and MDA-MB-231 breast cancer cell lines, RES decreased breast cancer cell mass and viability in a dose-dependent manner, concomitantly with an increase in SIRT1 and SIRT3 protein content." (PMID 31159437, 2019). "Regarding AKT depletion, however, the SIRT1-mediated proliferative effect is only partially decreased in breast cancer." (PMID 31817470, 2019). "SIRT1 rs3758391 was reported to be more common in Egyptian breast cancer patients than controls, as was rs1277836646." (PMID 30410074, 2018). "SIRT1 implication in the occurrence and progression of breast cancer pathogenesis have been identified and extensively investigated over recent years." (PMID 30093977, 2018). "Another study also showed that SIRT1 expression levels were significantly upregulated in breast cancer tissues, and SIRT1 overexpression eliminated the suppressive effects of the miR-22 overexpression on the malignant phenotype of MCF7 cells." (PMID 29752439, 2018). "Here we did two round screens of aging-related genes and identified SIRT1 as a central element regulating age-related CSCs in breast cancer." (PMID 30038266, 2018). "In breast cancer, both tumor-suppressive and tumor-promoting functions of SIRT1 have been reported and the controversy regarding SIRT1 role in the disease continues still." (PMID 30093977, 2018).
breast cancer (continued). "This study thus further consolidates the potential use of SIRT1 as a druggable epigenetic target in human breast cancer." (PMID 30093977, 2018). "This review provides a comprehensive examination of the various implications of SIRT1 in breast cancer development and metastasis." (PMID 30380732, 2018). "Collectively, the data suggest that SIRT1 blocks the transition between epithelial and mesenchymal state of breast cancer cells." (PMID 30038266, 2018). "For example, both breast cancer and hepatocellular carcinoma exhibit reduced SIRT1 levels compared with normal tissues." (PMID 29636061, 2018). "SIRT1 depletion enhances epithelial plasticity in basal-like breast cancer cells, induces highly proliferative MET-type ALDH1+ CSCs, confers cellular resistance to chemotherapy and promotes distant metastases." (PMID 30038266, 2018). "We showed that the opposite functions of SIRT1 in breast cancer are closely related to the molecular subtype." (PMID 30380732, 2018). "Recent studies have indicated that SIRT1 is expressed in various types of cancers, including colon cancer, breast cancer, Pca, squamous cell carcinoma, and lung cancer." (PMID 29416748, 2018). "Collectively, our data support the notion that PRRX1 instability, at least partially, underlies SIRT1 deficiency-induced epithelial plasticity and CSC properties of breast cancers." (PMID 30038266, 2018). "We also found that SIRT1 positively regulates aromatase transcription in breast cancer cells and binds the I.3/pII and pI.4 promoter regions." (PMID 30479694, 2018). "We also highlighted a SIRT1-dependent modulation of histones H3 and H4 acetylation patterns in breast cancer." (PMID 30093977, 2018). "We next did immunohistochemical analysis of KLF4 on 122 subjects of breast cancer to validate the association between KLF4 and SIRT1 and to elucidate the clinical relevance of KLF4 overexpression in patients with distal metastases." (PMID 30038266, 2018). "A study revealed that inhibitors of SIRT1/2 reduce FZD7 expression in breast cancer cell lines by decreasing β-catenin enrichment at the FZD7 promoter and that silencing FZD7 suppressed breast cancer cell migratory ability and cell growth." (PMID 29361730, 2018). "After ex-vivo studies on paired breast tumor/normal samples across all molecular subtypes, as well as in-vitro experiments on human mammary cell lines, we report that SIRT1 mediates the deacetylation of H3k4ac histone marker in breast cancer." (PMID 30093977, 2018). "Using a cohort of 135 human breast tumors and their matched normal tissues, as well as 5 human-derived cell lines, we identified H3k4ac as a new prime target of SIRT1 in breast cancer." (PMID 30093977, 2018). "In this study, we identified a new prime target of SIRT1 in breast cancer, the acetylated H3k4 histone mark (H3k4ac)." (PMID 30093977, 2018). "The authors showed that SIRT1 knockdown induces apoptosis, inhibits tumorigenesis, and enhances radiosensitivity of breast cancer cells." (PMID 30380732, 2018). "They concluded on the note that SIRT1 inhibits breast cancer development through diverse cellular processes, further establishing SIRT1 tumor-suppressive properties in breast cancer." (PMID 30380732, 2018). "In a previous study, we suggested a bivalent role of SIRT1 in breast cancer based on its differential expression patterns in human breast tumors." (PMID 30093977, 2018). "Further, low SIRT1 level predicts poor survival, chemotherapy-resistance and metastasis of breast cancer." (PMID 30038266, 2018). "Upregulation of SIRT1 has been reported in various human malignancies including prostate cancer, breast cancer, lung cancer, lymphoma, leukemia, soft tissue sarcomas, colon cancer, and gastric cancer." (PMID 29636061, 2018). "We began our in-vitro experiments by assessing the relative expression levels of SIRT1 and H3k4ac in 5 intrinsic subtype breast cancer cell lines using immunoblot analysis." (PMID 30093977, 2018).